IFNG (interferon gamma)
Diseases named in the same sentence as IFNG in open-access papers (continued):
Sharing a sentence is not in itself a finding about the gene and the disease.
malaria (continued). "Whilst a previous study of vectored malaria vaccines observed a reduction in T-cell immunogenicity in malaria exposed populations compared to UK volunteers, IFNγ responses in our volunteers receiving 5×1010 vp ChAd63 ME-TRAP were comparable with Phase Ia data." (PMID 23526949, 2013). "Mouse models of anti-malaria immune response indicate that interferon gamma and TH1 immune response play central roles in the developmental process." (PMID 24188121, 2013). "HMS patients in areas characterized by seasonal malaria develop high levels of anti-Csp antibody levels, and HMS is associated with an elevation of IFNγ and IL10 cytokines." (PMID 23533445, 2013). "In this same cohort, we have previously shown that in vitro IFNγ output from peripheral blood mononuclear cells in response to malaria parasites provides a correlate of cellular immunity to P. falciparum." (PMID 24040299, 2013). "Long term evaluation over a period of 9 months showed a decline of malaria-specific IFNγ responses in RAS and CPS mice that significantly correlated with loss of protection (r2 = 0.60, p<0.0001)." (PMID 22563506, 2012). "On top of quantitative analysis of CD8+ memory T cell responses, the present study supports the predictive value of malaria specific IFNγ response for longevity of protective immunity." (PMID 22563506, 2012). "Future in vivo studies in populations affected with malaria should explore the significance of IL-2 on the production of IFNγ at early stages of infection and in subjects with different degree of previous exposure to malarial antigens." (PMID 22316273, 2012). "After stimulus, the proportion of IFNγ-producing NK cells increased to 96.4 ± 3.5% in acute malaria patients and to 99.0 ± 3.6% in severe malaria patients." (PMID 22316273, 2012). "Such variations in IFNγ production has been seen in field studies of malaria, for instance, among other infectious diseases." (PMID 22229039, 2012). "In this model of malaria, all the inflammatory cytokines (TNFα, IFNγ, IL-1, IL-6, IL-18, IL-10) were found to be significantly elevated in the systemic circulation." (PMID 23323093, 2012). "The present study highlights the essential role of IFNγ response by liver memory CD8+ T cell for the longevity of protection against malaria." (PMID 22563506, 2012). "Underlying protective mechanisms of RAS protection in men show on short term malaria specific IFNγ responses." (PMID 22563506, 2012). "Further long term evaluation of RAS or CPS induced immune responses and protection clearly shows that up to 9 months after immunization, malaria specific IFNγ response declines despite sustained high levels of liver CD8+ TEM cells." (PMID 22563506, 2012). "NK cells were responsible for 2.4% of the total IFNγ production in subjects with acute malaria, and this proportion was significantly lower compared to the 6.64% observed in severe malaria patients." (PMID 22316273, 2012). "There was a small rise in non-malaria-specific background IFNγ responses (to culture medium alone) after the first vaccination with MVA-PP at low dose (1 × 108 pfu)." (PMID 21501642, 2011). "In agreement with the known anti-inflammatory properties of NO, malaria-infected mice receiving iNO had lower plasma levels of TNF, IFNγ and MCP-1, inflammatory markers associated with severe malaria." (PMID 22110737, 2011). "Consistent with findings by others, we show that ‘semi-innate’ γδT cells comprise the largest population of lymphocytes responding with IFNγ production to PfRBC in malaria-naïve donors." (PMID 22144890, 2011). "Apart from antibody-mediated immunity, cellular mechanisms such as the production of IFNγ-producing T cells are also important in mediating protection against blood stage malaria." (PMID 21920045, 2011). "A central mediator of such cellular immunological responses to the malaria parasite is the cytokine IFNγ." (PMID 22144890, 2011).
malaria (continued). "In mice which develop severe anaemic malaria, a transient early rise in IFNγ typically occurs, while in mice which develop CM, IFNγ levels remain high as the result of immune deregulation." (PMID 20051114, 2010). "Exposed not sensitized children also had 2- to 3-fold lower frequency of malaria antigen-driven IFNγ and/or IL-2 production (p<0.001) and higher IL-10 release (p<0.001) at 6-month follow-ups, when compared to sensitized and not-exposed children." (PMID 19636353, 2009). "These impaired antigen-specific Th1-type responses in putatively tolerant children were malaria-specific, since tetanus toxoid (TT)-driven IFNγ, IL-2, and/or lymphocyte proliferation responses were comparable between the three groups." (PMID 19636353, 2009). "NK cell are an important source of IFNγ and disruption of IFNγ signaling or NK cell depletion leads to increased parasitaemia and higher mortality in mouse models of malaria." (PMID 18612394, 2008). "Another factor thought to influence clinical outcome of malaria is the fine balance between the pro- and anti-inflammatory cytokines, such as TNFα, IFNγ and IL-10 produced during the infection, that modulate parasite–induced immune responses." (PMID 17460756, 2007). "CD8+ T lymphocytes are critical mediators of long-term protective immunity against malaria, killing intracellular liver stage parasites through interferon-gamma (IFN-γ), and/or other cytokines, and immune mediators, such as Granzyme B (GzB) that require direct contact with infected hepatocytes." (PMID 39946433, 2025). "As antigen-specific T cell responses have been shown to contribute to protection against pre-erythrocytic stage malaria parasites, the magnitude and specificity of vaccine-induced T cell responses was measured, using antigen-specific IFNγ production as a readout." (PMID 38675734, 2024). "However, we found higher BCG-specific IFNγ responses in the malaria-endemic versus urban setting (1·54 [1·20 to 1·98])." (PMID 39424574, 2024). "However, other studies suggest a role for IFNg in exacerbating severe malaria episodes (cerebral malaria), implying that a delicate balance of inflammatory cytokines is critical to regulate malarial disease and pathogenesis." (PMID 37465667, 2023). "In contrast, multigravid women had higher percentages of CD4+ T cells that produced TNFα in the absence of IFNγ, and these cells were associated with protection against malaria in pregnancy." (PMID 37634385, 2023). "To further characterise malaria-specific nnCD4+ T cell subsets at a molecular level, we performed RNA sequencing on IL-10+IFNγ+TNFα− and IL-10−IFNγ-TNFα+ nnCD4+ T cells isolated from three DPSP primigravid pregnant women at enrolment using a cytokine capture assay (>200 cells per sample)." (PMID 37634385, 2023). "The development of T-cell responses, major IFNγ-producing subsets during malaria, could also influence the outcome of a Plasmodium–ONNV coinfection in murine models." (PMID 35039441, 2022). "Here we showed that higher baseline frequencies and a subsequent early decrease of malaria-specific IFNγ+CD4+ T cells following PfSPZI DVI, which precedes the first detection of malaria parasite in the blood even by PCR, were associated with control of parasitemia." (PMID 35922467, 2022). "Instead, the inflammatory IFNγ cytokine milieu during malaria and Th1-cTfh cells activated by parasite simulation have been implicated in the induction of Tbet+ ‘atypical’ MBC responses, which have been previously thought to have exhausted phenotypes and contribute to slow acquisition of immunity." (PMID 36845571, 2021). "The malaria-naive GLA-SE group unexpectedly showed low IFNγ responses, which may be explained by the relatively low dose of GLA (2.5 μg) used in the current study." (PMID 33854065, 2021). "First, Tfh cells have been observed to produce IFNγ alongside IL-21 during murine malaria." (PMID 36845571, 2021).
malaria (continued). "Recent work in a mouse model also supports the hypothesis that excessive type-I interferon inhibits the production of malaria-specific IFNγ producing CD8+ T cells." (PMID 34243763, 2021). "All immune system components characteristically seen in persons with acquired immunity for malaria, like natural killer cells, interferon (interferon gamma and type 1interferon) and immunoglobin G, should be evaluated among symptomatic and asymptomatic patients with COVID-19." (PMID 35233116, 2021). "Given that Tr1-derived IFNγ and IL-10 cytokines negatively regulated Tfh cell responses in mice models of malaria, overcoming or blocking parasite-specific Tr1 cells in malaria-exposed children may be required to optimize vaccine responsiveness." (PMID 36845571, 2021). "However, to date, no studies have investigated the impact of Tr1 cells on Tfh cell development during malaria in humans, despite an important agonistic role of IFNγ and IL-10 on Tfh during murine Plasmodium infection." (PMID 36845571, 2021). "In chronic infections such as malaria, elevated levels of IFNγ are seen locally in the gut." (PMID 33799736, 2021). "IFNG+2200 SNPs and markers of iron status at the end of the malaria season." (PMID 32420456, 2020). "Together, these results demonstrate that Vδ2 T cells that are refractory to stimulation by malaria antigen alone can nonetheless produce IFNγ and degranulate when activated through CD16, suggesting a potential physiologic role for antibody engagement in the activation of Vδ2 cells." (PMID 33085728, 2020). "IFNG haplotypes and markers of iron status at the end of the malaria season." (PMID 32420456, 2020). "Vaccines against blood-stage malaria often aim to induce antibodies to neutralize parasite entry into red blood cells, interferon gamma (IFNγ) produced by T helper 1 (Th1) CD4+ T cells or interleukin 4 (IL-4) produced by T helper 2 (Th2) cells to provide B cell help." (PMID 33153189, 2020). "This pattern of reduced expression of IFNG mRNA in the convalescent samples mirrors our previously published observations for CD4+CD38high cells from healthy volunteers (malaria‐naïve Australian volunteers) and for CD4+CD38high cells from CHMI volunteers at day 7 of infection." (PMID 33282291, 2020). "Similar RNA profiles were obtained for both the CHMI subjects and symptomatic, malaria-experienced adults, with increases in IFNγ, TNFα, IL-1β, as well as the related nuclear factor kappa-light-chain-enhancer of activated B cells (NFκB) signaling and regulatory cascades." (PMID 31900030, 2020). "Importantly, activation of NAS-TLRs during malaria is important to trigger IL-12, which is necessary for maximal IFNγ response during acute infection with malaria." (PMID 32929083, 2020). "It has been reported that imbalance of cytokines such as tumor necrosis factor alpha (TNF-α), interleukin-6 (IL-6), IL-10 and interferon gamma (IFN-γ) resulting from malaria related-inflammation can induce changes in iron absorption and distribution (iron delocalization)." (PMID 31760954, 2019). "In experimental malaria caused by P. yoelli infection of C57BL/6 mice, B cell intrinsic IL-10 signaling enhanced germinal center (GC) B cell responses by limiting IFNγ activity and subsequent Tbet expression by these cells, thereby promoting antibody production and parasite clearance." (PMID 30809232, 2019). "In order to evaluate the EXP1-specific T cell response on an epitope level, we first looked at the ex vivo IFNγ production of PBMCs of acutely infected malaria patients after stimulation with single peptides of an overlapping 13-17-mer peptide set covering the entire P. falciparum antigen EXP1." (PMID 32038611, 2019). "This demonstrates the importance of IFNγ production for protection against malaria." (PMID 30949162, 2019). "Importantly, immunization with PSNPs-MSP4/5 induced partial protection against malaria blood-stage infection (50–80%) shown to be mechanistically dependent on interferon gamma (IFN-γ) production." (PMID 30930890, 2019).
malaria (continued). "Furthermore, cytokines such as TNFα and IFNγ which are released during malaria infection, suppress hematopoiesis and hence contribute to anemia, another main pathology of malaria." (PMID 29495555, 2018). "More recent studies in non-human primate macaque models for P. vivax infection showed that during acute malaria, monocytes loaded with hemozoin suppress erythropoiesis in the bone marrow by inducing apoptosis of the erythroid progenitors via IFNγ and antagonization of GATA1 transcriptional networks." (PMID 30581439, 2018). "In ex vivo analysis of cord blood from mothers in an endemic setting who had experienced malaria during pregnancy, the Vγ9Vδ2 T-cells produced significantly more IFNγ and TNFα than those from healthy mothers, as did the peripheral Vγ9Vδ2 T-cells from the mother." (PMID 30538708, 2018). "We found that higher frequencies of Vδ2+ T cells, as well as higher percentages of Vδ2+ T cells that produced IFNγ and TNF upon malaria antigen stimulation, were both associated with a significantly lower odds of subsequent P. falciparum infection in the subsequent year." (PMID 28904345, 2017). "Together, these data suggest that a final switch from IFNγ to IL10 production among malaria-specific CD4+ T cells may play a role for in mediating tolerance to malaria." (PMID 29097996, 2017). "Finally, we show that innate IFNγ production is important in mediating protection in a mouse model of vaccination against malaria." (PMID 29263880, 2017). "Although inflammatory responses, including interferon gamma (IFN-γ), IL-12, IL-1β, IL-2, and TNF-α, play important roles that facilitate parasite clearance, circulating high levels of these cytokines have been associated with malaria immunopathology." (PMID 28399920, 2017). "In the few published studies which have used multicolor flow cytometry to assess Pf-specific cytokine production by CD4 T cells at an individual cell level, it has been shown that the Pf-specific CD4 T-cell response in highly malaria-exposed children is dominated by IFNγ and IL10 coproducing cells." (PMID 29097996, 2017). "This concept is further supported by the observation by us and others that IFNγ to IL10 ratios might be altered in patients with severe malaria." (PMID 27802341, 2016). "Disrupting type I IFN signaling is also known to promote enhanced IFNγ production, a cytokine exhibiting protective effects during malaria, and this may account for these seemingly discrepant findings." (PMID 27792766, 2016). "Recent data has suggested that increased Th1 responses might suppress Tfh cells via IFNγ-signalling in experimental malaria, and viral infection." (PMID 27812214, 2016). "Thus, the PBMC of malaria patients were stimulated with iRBC and their production of IFNγ, IL10, TNFα, and IL13 was measured by intracellular staining." (PMID 27802341, 2016). "Importantly, we also noticed a trend towards a decreased IL10+ to IFNγ+ T cell ratio in our patients with severe cerebral malaria compared to patients with uncomplicated malaria but our sample size of patients with severe cerebral malaria was low (n = 3)." (PMID 27802341, 2016). "We previously reported that recent malaria exposure can dampen subsequent P. falciparum-induced inflammation via a regulatory state mediated in part by the anti-inflammatory cytokine IL-10 produced by CD4+CD25+Foxp3- T cells that also produce IFNγ and TNF5." (PMID 27506615, 2016). "Our data suggest a graded activation of pathways downstream of the pro-inflammatory cytokines IFNγ, TNF, and IL-1β that is associated with prior malaria-exposure, with naïve individuals having the greatest activation and malaria-experienced asymptomatic individuals having the least." (PMID 27506615, 2016).
malaria (continued). "A DNA prime/adenovirus boost malaria vaccine encoding Plasmodium falciparum strain 3D7 CSP and AMA1 elicited sterile clinical protection associated with CD8+ T cell interferon-gamma (IFN-γ) cells responses directed to HLA class 1-restricted AMA1 epitopes of the vaccine strain 3D7." (PMID 27695088, 2016). "Indeed, the macrophage inflammatory protein MIP3-α/CCL20 and the monokine induced by interferon-gamma MIG/CXCL9 were found elevated in infants with severe malaria and in patients with atopic dermatitis." (PMID 25698903, 2015). "We found that whilst diminished levels of lipid peroxidation-derived aldehydes and TNFα were detected in animals with malaria that had been treated with capsazepine, IFNγ production remained similar to that observed for samples obtained from vehicle-infected mice." (PMID 25242870, 2014). "Tumour necrosis factor (TNF) and interferon gamma (IFN-γ), encoded by TNF-836 C/A (rs 1800630) and IFN-γ -1616 C/T (rs2069705) genes, are key immunological mediators that are believed to both play protective and pathological roles in malaria." (PMID 25124540, 2014). "Indeed, high systemic levels of inflammatory mediators such as TNFα, IFNγ, and aldehydes are correlated with severe malaria in humans." (PMID 25242870, 2014). "CD8+ T lymphocytes are important mediators of protective immunity against the malaria liver stages, killing the intracellular parasites through interferon-gamma (IFN-γ) or release of cytotoxins, and thus could provide an effective objective for immunization." (PMID 25211344, 2014). "In univariate Cox proportional hazards analysis evaluating time to next episode of malaria, a higher frequency of CD4+ T cells producing any IFNγ or IL10, or the combinations IFNγ+/IL-10+/TNFα− and IFNγ−/IL-10+/TNFα− was associated with a significantly increased hazard of malaria (left columns)." (PMID 24415936, 2014). "Both IL-10-producing CD4+ T cells and IFNγ-producing CD4+ T cells were present at higher frequencies among children with a higher prior incidence of malaria (≥2 episodes ppy) than among those with a lower prior incidence (<2 episodes ppy, P<0.001 and P = 0.02, respectively)." (PMID 24415936, 2014). "More recently, Gitau and colleagues described malaria-specific co-production of IFNγ and IL-10 following stimulation of CD4+ T cells with a variety of expressed PfEMP variants, although these co-producing cells represented a minor fraction of the total antigen-specific CD4+ T cell response." (PMID 24415936, 2014). "In addition, prior studies have shown that IL-10 blockade increases malaria-specific IFNγ cytokine production in filaria-coinfected individuals and in cord blood mononuclear cells from neonates born to mothers exposed to malaria." (PMID 24415936, 2014). "Malaria also triggered the release of TNFα and IFNγ in both infected groups." (PMID 25242870, 2014). "Interferon gamma plays a central role in immune response against malaria." (PMID 24188121, 2013). "Most recently, heterologous prime boost immunization with chimpanzee adenovirus 63 (ChAd63) followed by MVA, both expressing ME-TRAP, has been shown to be the most immunogenic vaccine regimen to date, inducing more than 2000 IFNγ producing T cells post MVA boost in malaria naïve volunteers." (PMID 23526949, 2013). "Interferon gamma and many interferon gamma-related genes were also up-regulated after malaria." (PMID 24188121, 2013). "IFNγ potently enhances FcR-mediated monocyte/macrophage phagocytosis and ROS, and may function to promote opsonising immunity to malaria." (PMID 24040299, 2013). "A mean 76.7 ± 2.3% of NK cells from acute malaria patients produced IFNγ." (PMID 22316273, 2012). "In patients with severe malaria, 94.6 ± 2.4% of NK cells were IFNγ producers." (PMID 22316273, 2012).